WDR86 (WD repeat domain 86)
Tractability: No criterion of Open Targets' tractability assessment is met for any kind of drug.
Gene: Protein-coding gene on chromosome 7 (151,375,909 to 151,410,727, reverse strand). Ensembl gene ENSG00000187260.
Subcellular location (Human Protein Atlas): Nucleoplasm; Cytosol; Plasma membrane
Genetic constraint (gnomAD): Loss-of-function variants: 24 observed, 23.51 expected, observed/expected ratio (o/e) 1.02, 90% interval 0.74 to 1.43. The upper end of that interval is the gene's LOEUF score, 1.43, which puts it in group 5 of 6, group 1 being the genes least tolerant of losing a copy. Missense variants: 485 observed, 422.56 expected, observed/expected ratio (o/e) 1.15, 90% interval 1.07 to 1.24. Synonymous variants: 222 observed, 186.54 expected, observed/expected ratio (o/e) 1.19, 90% interval 1.07 to 1.33.
Homologues: Orthologues: rabbit WDR86 (93% identical), pig WDR86 (93% identical), mouse Wdr86 (88% identical), rat Wdr86 (88% identical), guinea pig WDR86 (87% identical), dog WDR86 (83% identical), macaque WDR86 (79% identical), chimpanzee WDR86 (74% identical), tropical clawed frog wdr86 (62% identical), Caenorhabditis elegans sel-10 (28% identical). Paralogues in human: FBXW7 (29% identical), BTRC (22% identical), FBXW11 (22% identical), TRAF7 (20% identical), FBXW9 (18% identical), WDR49 (17% identical), WDR64 (17% identical), EFCAB8 (16% identical), FBXW8 (15% identical), FBXW12 (13% identical), PAAF1 (12% identical), WDR54 (11% identical), and 2 more.
Diseases named in the same sentence as WDR86 in open-access papers:
WDR86 is named in the same sentence as 5 diseases in open-access papers, as found by Europe PMC text mining. Sharing a sentence is not in itself a finding about the gene and the disease. The quoted sentences say what the papers report.
breast carcinoma (2 papers, 2020 to 2021). "WDR86 expression is linked to poor survival in colorectal carcinoma and breast carcinoma." (PMID 34090518, 2021). "To test the function of the two downregulated ABC genes, ALX4 and WDR86, we ectopically introduced their cDNA via a lentiviral vector to increase their expression in the breast cancer cell lines." (PMID 32539762, 2020). "To confirm our findings from the in vitro assays, we next examined the effect of overexpression of ALX4 or WDR86 on breast cancer cell growth in a xenograft model in vivo." (PMID 32539762, 2020).
thyroid (1 paper, 2021). "The 11 selected thyroid-specific RNA transcripts (TPO, TG, GFRA2, IYD, PDE8B, WDR86, C16orf89, DGKI, DIO2, TSHR, and PAX8) were amplified from healthy volunteers and thyroid patients." (PMID 34512731, 2021).
cancer (2 papers, 2020 to 2022). A tumor composed of atypical neoplastic, often pleomorphic cells that invade other tissues. "There are few studies on WD repeat domain 86 (WDR86) and MAS related GPR family member F (MRGPRF) in cancer." (PMID 35132081, 2022).
tumor (1 paper, 2020). "It is proposed that one of the paralogs of WDR86 is TRAF7, which has been implicated as a tumor suppressor by inducing apoptosis." (PMID 32539762, 2020). "Lastly, we also studied the extent to which WDR86 could play as a tumor suppressor." (PMID 32539762, 2020). "In contrast, overexpression of WDR86 did not inhibit tumor progression, which is consistent with the in vitro data." (PMID 32539762, 2020). "Therefore, WDR86 may function as a potential tumor suppressor although we did not observe a malignancy-inhibitory activity of WDR86 with the assays we used." (PMID 32539762, 2020).
WDR86 also shares sentences with these, for which no sentence is quoted: colorectal carcinoma (1 paper).